IL33 (interleukin 33)
Diseases named in the same sentence as IL33 in open-access papers (continued):
Sharing a sentence is not in itself a finding about the gene and the disease.
tumor (continued). "In studies of IL-33 in the context of cancer, Il33−/− mice and Il1rl1−/− mice have been shown to have greater tumor growth." (PMID 38825642, 2024). "The multifaceted roles of IL-33 in tumor progression have sparked controversy within the scientific community." (PMID 38825642, 2024). "Future studies are necessary to understand the mechanisms by which IL-33 is a pro-tumour cytokine during SCC and provide insight for developing novel therapeutics against SCC in clinical practice." (PMID 38662248, 2024). "IL-33 combined with p38 signaling pathway inhibitor synergistically enhances the anti-tumor response of abdominal dissemination in GC." (PMID 38238529, 2024). "In particular, IL-33 can stimulate eosinophil-dependent anti-tumor immunity in various tumor models." (PMID 39061080, 2024). "Following incorporation into target tumor cells, EV from IL-33-activated eosinophils transcriptionally reprogram tumor cells to inhibit cancer proliferation and malignant progression." (PMID 39061080, 2024). "In summary, IL-33 is a multifaceted cytokine with the potential to shape the tumor microenvironment." (PMID 38825642, 2024). "Analysis of the immune response in tumour-draining lymph nodes showed that the percentage of CD4+IFNγ+ cells was significantly higher in anti-IL-33 treated mice." (PMID 38662248, 2024). "Given the potential of IL-33 as an adjuvant and a stimulator of DCs, IL-33 has emerged as a pivotal candidate for successful DC-based tumor immunotherapy." (PMID 38825642, 2024). "In contrast, another study identified Il33 as a main target of the gene regulatory programs that allow the “acinar-to-neoplasia” switch and the initiation of PC in the context of KRAS mutations." (PMID 38942797, 2024). "IL-33 has been demonstrated to be a promising biomarker for tumor diagnosis, prognosis prediction, and therapy response in several cancer types." (PMID 39839625, 2024). "In the presence of IL-33, ILC2s can enhance anti-tumor immunity by upregulating MHC-I expression on tumor cells and improving their recognition and elimination by cytotoxic T lymphocytes." (PMID 38524132, 2024). "This IL-25 primes eosinophils and works synergistically with other cytokines like IL-33 and increase their anti-tumor activity." (PMID 38892286, 2024). "IL-33 is expressed by several cell types within the tumour microenvironment and exhibits different or even opposite functions under varying circumstances." (PMID 38662248, 2024). "IL-33 is a pleiotropic cytokine with dual roles, modulating either pro-tumoral or anti-tumoral immune responses within the tumor microenvironment." (PMID 38881897, 2024). "While cisplatin alone partially reduced tumor growth, as indicated by volume, size, and weight, combining it with α-IL-33 or α-ST2L significantly enhanced tumor suppression." (PMID 38778059, 2024). "Recently, it has been reported that the IL-33–transforming growth factor beta (TGFβ) signalling loop that connects tumour-initiating cells and FcERIα+ macrophages." (PMID 38662248, 2024). "In the tumor environment, endogenous IL-33 contributes to the recruitment and M2 polarization of TAMs, which secrete MMP9 or TGF-β to promote cancer progression and metastasis." (PMID 38825642, 2024). "This highlights the crucial roles of IL-33 and the tumor’s mycobiome in PDAC progression and potential treatment strategies." (PMID 38835055, 2024). "Considering the observed low expression of IL-33 mRNA in the tumor cells derived from malignant ascites, we further evaluated the antitumor effect of IL-33 in abdominal dissemination tumors." (PMID 38238529, 2024). "This study deepens our understanding of the complex dynamics within the tumor microenvironment by demonstrating in vivo the earlier discovered inverse correlation between the number of ILC2s and tumor size in the IL-33-treated animals." (PMID 38524132, 2024). "The cytokine IL-33 has a dual role in the tumor microenvironment (TME), promoting and inhibiting tumor growth." (PMID 40236667, 2024).
tumor (continued). "Despite of the stable maintenance of type 2 identity observed in the majority of the total ILC2s across different conditions, other clusters seem to have immunological plasticity that responds to the presence of tumour growth and IL33/TSLP stimulation." (PMID 38172434, 2024). "Overall, these results indicate that EV from IL-33 activated eosinophils affect epithelial to mesenchymal transition (EMT)-related gene program in target tumor cells shaping their phenotype towards a less metastatic potential." (PMID 39061080, 2024). "In the present study, we have investigated the impact of IL-33 activation on EV release by mouse and human eosinophils and the effects of eosinophil-derived EV in shaping the phenotype of tumor cells." (PMID 39061080, 2024). "In certain tumor indications, other immune cell populations have been described as important mediators for the antitumor effect of IL-33." (PMID 38881897, 2024). "This protein, known as IL-33trap, was able to neutralize IL-33 in the tumor microenvironment and efficiently reduced ST2-expressing tumor-associated macrophages, thereby limiting the infiltration of immune-suppressive cells." (PMID 38881897, 2024). "By using ST2 KO mice, several groups have demonstrated the essential role of this receptor for the antitumor activity of IL-33 in different tumor models." (PMID 38881897, 2024). "Therapeutic overexpression of IL-33 in tumor epithelial cells promotes type 1 antitumor immune responses through CD8+ T cells and NK cells." (PMID 40236667, 2024). "Intranuclear IL-33 affects Tregs’ transcriptional profile and determines their activity in the anti-tumor immune response." (PMID 39227959, 2024). "There is also evidence that a novel paracrine axis comprising GPNMB and IL-33 is activated by interactions between macrophages and tumor cells, ultimately promoting tumor cell survival, cancer stem cell expansion and metastasis development." (PMID 38351314, 2024). "This review covers the general characteristics of IL-33 and its effects on tumor growth, with detailed information on the immunological mechanisms associated with dendritic cells (DCs)." (PMID 38825642, 2024). "Emerging preclinical studies are investigating IL-33/ST2L axis blockade to enhance anti-tumor immune response and overcome chemoresistance." (PMID 38778059, 2024). "The expression of IL33 by tumor cells induces the production of eotaxin 1, leading to eosinophil recruitment and degranulation-dependent suppression of tumor growth." (PMID 39024248, 2024). "These approaches aim to translate the observed antitumor effects of IL-33 in mice to effective DC-based tumor immunotherapy in humans." (PMID 38825642, 2024). "Despite of this, based on the transcriptional profiles, ILC2 is a heterogeneous population wired with functional plasticity promoted by growing tumour environment, and this plasticity can be further inflated by IL33/TSLP stimulation." (PMID 38172434, 2024). "We downloaded the RNA sequencing (RNA-seq) data from TCGA-STAD, GTEx, and GEO data sets to evaluate the expression of IL-33 mRNA in normal tissues, tumor tissues, and tumor cells derived from malignant ascites." (PMID 38238529, 2024). "Despite its antitumor effects, the complex interplay of IL-33 within the tumor microenvironment underscores the need for further investigation." (PMID 38881897, 2024). "The staining intensity of IL-33 in normal tissues was higher than that in tumor tissues (P = 0.0476)." (PMID 38238529, 2024). "In this study, we extend our previous studies on the importance of ILC2s in promoting Th1-dependent CTL anti-tumor responses and thereby make several novel observations related to the potential of IL-33/ILC2 axis to confer immune protection against tumors." (PMID 38524132, 2024). "IL‐33 promotes regeneration in hepatic resection models, and the deficiency of IL‐33 or its receptor ST2 leads to tumour growth inhibition and liver regeneration delay." (PMID 39152680, 2024).
tumor (continued). "IL-33-induced amplification of ILC2s inhibits the activation of NK cells and their cytotoxic effects, thereby promoting tumor growth." (PMID 39309440, 2024). "The presence of IL-33 also exerted biological alterations directly on the tumour cells, leading to increased motility and proliferation." (PMID 38662248, 2024). "Increased number of eosinophils in human tumor sections with higher IL-33 levels was detected, when compared to human tumor sections with lower IL-33 levels." (PMID 38524132, 2024). "In the LLC allograft model, we assessed the anti-tumor effects of α-IL-33 or α-ST2L alone and in combination with cisplatin." (PMID 38778059, 2024). "Remarkably, either deleting IL-33 genetically or administering anti-fungal treatment leads to PDAC tumor regression." (PMID 38835055, 2024). "In a pan‐cancer context, IL33 emerged as a potential tumour‐inhibitor, influencing immune‐related molecules." (PMID 38923705, 2024). "In our GC tumor model, the increase of IL-33 levels locally resulted in the recruitment of CD8+T cells, NK cells, DCs, and macrophages and increased the expression of IFN-γ in CD8+ T cells and NK cells, indicating the activation of immunologic effector cells." (PMID 38238529, 2024). "High Il33 expression in tumor cells recruits and activates TH2 and ILC2 cells which secrete pro-tumorigenic cytokines such as Il4, Il5, and Il13." (PMID 38942797, 2024). "Recent studies address the role of IL33 in the context of PC and both, tumor-promoting and tumor-suppressing activities are discussed." (PMID 38942797, 2024). "IL-33 can induce polyploidization of tumor cells, leading to tumor progression and metastasis, making it a potential biomarker and drug target for cancer treatment." (PMID 39055650, 2024). "Combinatorial treatments leveraging IL-33 exhibit enhanced antitumor efficacy across different tumor models, promising novel avenues for cancer therapy." (PMID 38881897, 2024). "Pro-inflammatory cytokines such as IL-6, IL-8, IL-31, and IL-33 promote tumor growth and resistance to apoptosis." (PMID 38464838, 2024). "In the context of the Hallmark gene set analysis, the upregulation of angiogenesis, EMT, and inflammatory response underscores IL33's potential to enhance tumour vascularization, and invasiveness, and create a pro‐inflammatory tumour microenvironment." (PMID 38923705, 2024). "The co-administration of IL-33 and PD-1 blockade demonstrates an inhibitory effect on tumor growth, accompanied by an augmented presence of intra-tumoral ILC2s, particularly the mILC2s phenotype (ST2+KLRG+ ILC2s)." (PMID 38430390, 2024). "In conclusion, our study provides a possible mechanism by which IL-33 stimulates the anticancer activities of eosinophils through EV-mediated reprogramming of tumor cells and opens new perspectives on the use of eosinophil-derived EV in cancer therapy." (PMID 39061080, 2024). "The expression of IL-33 mRNA decreased in purified tumors from ascites compared with normal and primary tumor tissues." (PMID 38238529, 2024). "For instance, in certain cancers, IL‐33 expression correlates with tumour cell proliferation, invasive capabilities and poor prognosis." (PMID 38923705, 2024). "The results revealed a discernible increase in the number of eosinophils in tumor sections exhibiting higher IL-33 levels compared to those with lower IL-33 levels." (PMID 38524132, 2024). "In particular, the presence of ILC2s significantly inhibited tumor formation in WT chimeric mice bearing tumors expressing IL-33, when compared to RORa−/− chimeras, suggesting the role of IL-33/ILC2s axis in mediating the anti-tumor immunity." (PMID 38524132, 2024). "Analysis of human SCC biopsies showed the presence of IL-33 in epithelial cells as well as the tumour surroundings." (PMID 38662248, 2024).
tumor (continued). "Conversely, IL-33 inhibits tumour growth by enhancing the activation of natural killer (NK) cells and cytotoxic CD8+ T cells, whereas mice lacking ST2 show attenuated SCC progression due to increased NK cell–mediated cytotoxicity." (PMID 38662248, 2024). "We found that mouse and human IL-33 activated eosinophil-derived EV affect the transcriptional program of target tumor cells towards a block of cell cycle and malignant progression." (PMID 39061080, 2024). "Few studies addressed the role of MCs in PDAC and reported their impact on angiogenesis and tumor cell migration predominantly via the release of Il13, which was among the top up-regulated factors released by MCs upon IL33-dependent stimulation." (PMID 38942797, 2024). "Research shows that suppressive CD4+ Foxp3+ GATA3+ Treg cells proliferate in response to ST2/IL-33 signaling, both in vivo and in vitro, which aids in immunosuppression and tumor immune evasion." (PMID 40236667, 2024). "Recognizing the pivotal role of the immunogenicity of DC vaccines in DC-based tumor immunotherapy, we propose compelling methods to enhance this immunogenicity through the addition of IL-33 and the promotion of highly immunogenic DC generation." (PMID 38825642, 2024). "This intriguing observation, where smaller tumors harbor a higher count and frequency of ILC2s in response to IL-33 treatment, marks a significant departure from the conventional understanding of tumor-immune interactions." (PMID 38524132, 2024). "Recent discoveries regarding their role in actuating cytolytic T lymphocyte responses, including curbing tumor growth rates and hindering metastasis, have added a new dimension to our understanding of the IL-33/ILC2 axis." (PMID 38524132, 2024). "Recruitment and education of Gr1+CD11b+ cells in the TME, particularly through the chemokines CCL2, CXCL1, and CXCL2 or IL-33, are considered critical steps for their contribution to tumor progression and metastasis." (PMID 38236642, 2024). "We examined the in vivo effect of IL-33 activation on tILC2s in tumor-bearing mice in terms of their overall yield, the ability to infiltrate tumor mass, and their effect on the tumor weight." (PMID 38524132, 2024). "Overall, these findings suggested that RRM2, SLC2A1, DDIT4, and VDAC2 were potential oncogene, whereas PEBP1 and IL33 were candidate tumor suppressor genes." (PMID 39311766, 2024). "Here, we evaluated the anti-tumor activities of eosinophil-derived EV following activation with the alarmin IL-33." (PMID 39061080, 2024). "In this study, we aimed to evaluate the role of IL-33 on the biology of the tumour cells and the T cell activation status during SCC." (PMID 38662248, 2024). "Factors secreted by tumor cells, such as MIC-1, CSF-1, TGF-β, and IL-33, impair the anti-tumor functions of microglia." (PMID 37307835, 2024). "In this context, our study provides the first demonstration of a link between anti-tumor activities of eosinophils mediated by EV release following activation with IL-33." (PMID 39061080, 2024). "The tumor and spleen were collected and analyzed by flow cytometry at the treatment endpoint to evaluate the influence of IL-33 on the TIME." (PMID 38238529, 2024). "By stimulating the growth of suppressive Treg cells and influencing Th cell differentiation, IL-33 regulates adaptive immune responses within the tumor." (PMID 40236667, 2024). "Poor responders showed elevated IL-33 levels and increased infiltrating Rab37+ST2L+CD206+ tumor-associated M2 macrophages (yellow arrow)." (PMID 38778059, 2024). "Blocking IL-33 in vivo resulted in a skewing of the Th1 immune profile and, consequently, a reduction in the tumour burden after SCC development." (PMID 38662248, 2024). "Some reports suggest that endogenous IL-33 can also induce antitumor immunity by overcoming IL-33-induced Treg expansion or boosting tumor-infiltrating ILC2s39,40." (PMID 38825642, 2024).
tumor (continued). "IL-11 is known to stimulate proinflammatory responses, including IL-6 and IL-33, through the JAK–STAT pathway in tissue fibroblasts, of which cancer-associated fibroblasts contribute centrally to the tumor microenvironment." (PMID 39329890, 2024). "The IL-33/ST2 axis plays an important immunomodulating in the tumour microenvironment, where it acts on immune cell populations associated with type 2 and regulatory immunity." (PMID 38662248, 2024). "Exogenous IL-33 also contributes to inhibiting tumor growth by overcoming IL-33-mediated Treg expansion." (PMID 38825642, 2024). "Despite the well-established pro-tumor activity of IL-33, this cytokine has been shown to potentiate Th1-mediated immune responses, the most relevant in tackling cancer." (PMID 38881897, 2024). "IL-33, a secreted alarmin cytokine that plays an important role in type II innate immunity, is known to be upregulated in NSCLC patients associated with tumor malignancy." (PMID 39329890, 2024). "This pivotal discovery demonstrated that IL-33-dependent ILC2s play a functional role in IL-33-mediated anti-tumor immunity." (PMID 38524132, 2024). "Recent research indicates that interleukin-33 (IL-33) is a key factor in the formation of PGCCs and is crucial in tumor polyploidization." (PMID 39055650, 2024). "The tumor weight (P = 0.0032) and the number of mesenteric dissemination tumor nodules (P = 0.0022) of mice with IL-33 treatment also decreased." (PMID 38238529, 2024). "IL-33 significantly affects myeloid-derived suppressor cells (MDSCs), which are critical mediators of immune suppression within the tumor." (PMID 40236667, 2024). "The in vivo mouse experiments showed that IL-33 treatment induced the recruitment of eosinophils and reduced the number of intrahepatic tumor nodules." (PMID 39308686, 2024). "Higher expression of IL-33 protein was observed in normal tissues (black arrows) than in tumor tissues (red arrows)." (PMID 38238529, 2024). "According to research conducted by Jacquelot and others, IL-33 has the ability to enhance tumor sensitivity to PD-1 by activating ILC2." (PMID 38384457, 2024). "When combined with IL-12, IL-33 further enhances NK cell activation, improving their ability to destroy tumor cells through cytotoxicity." (PMID 40236667, 2024). "IL-33 exerts pro-tumor activity, including PPAR-gamma-mediated delivery of IL-4, IL-13, and IL-15 from ILC2s." (PMID 39119332, 2024). "For instance, ILC2s have been shown to both suppress NK cell-mediated tumor cytotoxicity via interleukin-33 in melanoma and to promote MDSC differentiation and tumor establishment." (PMID 38339226, 2024). "Immunohistochemistry was utilized to detect IL-33 expression in tumor tissues, while immunofluorescence was employed to confirm the infiltration of ILC2s in both murine and human tumor tissues." (PMID 38430390, 2024). "Taken together, IL-22-regulated Il33 was specifically related to hepatocyte proliferation, whereas Steap4 was involved both in hepatocyte proliferation and tumor progression." (PMID 38533053, 2024). "The intricate interplay between IL-33 and various immune cells highlights its potential impact on tumor immunity." (PMID 38825642, 2024). "Our studies underscore novel IL-33-stimulated anticancer activities of eosinophils through EV-mediated reprogramming of tumor cells opening perspectives on the use of eosinophil-derived EV in cancer therapy." (PMID 39061080, 2024). "The analysis of HIF-1α alone showed a more significant correlation with certain prognostic features of CRC than when HIF-1α was analyzed on the basis of VEGF and IL-33 expressions in tumor cells." (PMID 38313904, 2024). "Conversely, IL-33 can inhibit tumor growth by interacting with the T cell receptor (TCR) and IL-12 signaling, enhancing the effectiveness of CD8+ T cells." (PMID 40236667, 2024). "Prevalence of IL-33 expression in tumor cells among CRC patients with general clinicopathological characteristics." (PMID 38313904, 2024).